PARK7 (Parkinsonism associated deglycase)
Description:
Multifunctional protein with controversial molecular function which plays an important role in cell protection against oxidative stress and cell death acting as oxidative stress sensor and redox-sensitive chaperone and protease. It is involved in neuroprotective mechanisms like the stabilization of NFE2L2 and PINK1 proteins, male fertility as a positive regulator of androgen signaling pathway as well as cell growth and transformation through, for instance, the modulation of NF-kappa-B signaling pathway. Has been described as a protein and nucleotide deglycase that catalyzes the deglycation of the Maillard adducts formed between amino groups of proteins or nucleotides and reactive carbonyl groups of glyoxals. But this function is rebuted by other works. As a protein deglycase, repairs methylglyoxal- and glyoxal-glycated proteins, and releases repaired proteins and lactate or glycolate, respectively. Deglycates cysteine, arginine and lysine residues in proteins, and thus reactivates these proteins by reversing glycation by glyoxals. Acts on early glycation intermediates (hemithioacetals and aminocarbinols), preventing the formation of advanced glycation endproducts (AGE) that cause irreversible damage. Also functions as a nucleotide deglycase able to repair glycated guanine in the free nucleotide pool (GTP, GDP, GMP, dGTP) and in DNA and RNA. Is thus involved in a major nucleotide repair system named guanine glycation repair (GG repair), dedicated to reversing methylglyoxal and glyoxal damage via nucleotide sanitization and direct nucleic acid repair. Protects histones from adduction by methylglyoxal, controls the levels of methylglyoxal-derived argininine modifications on chromatin. Able to remove the glycations and restore histone 3, histone glycation disrupts both local and global chromatin architecture by altering histone-DNA interactions as well as histone acetylation and ubiquitination levels. Displays a very low glyoxalase activity that may reflect its deglycase activity. Eliminates hydrogen peroxide and protects cells against hydrogen peroxide-induced cell death. Required for correct mitochondrial morphology and function as well as for autophagy of dysfunctional mitochondria. Plays a role in regulating expression or stability of the mitochondrial uncoupling proteins SLC25A14 and SLC25A27 in dopaminergic neurons of the substantia nigra pars compacta and attenuates the oxidative stress induced by calcium entry into the neurons via L-type channels during pacemaking. Regulates astrocyte inflammatory responses, may modulate lipid rafts-dependent endocytosis in astrocytes and neuronal cells. In pancreatic islets, involved in the maintenance of mitochondrial reactive oxygen species (ROS) levels and glucose homeostasis in an age- and diet dependent manner. Protects pancreatic beta cells from cell death induced by inflammatory and cytotoxic setting (By similarity). Binds to a number of mRNAs containing multiple copies of GG or CC motifs and partially inhibits their translation but dissociates following oxidative stress. Metal-binding protein able to bind copper as well as toxic mercury ions, enhances the cell protection mechanism against induced metal toxicity. In macrophages, interacts with the NADPH oxidase subunit NCF1 to direct NADPH oxidase-dependent ROS production, and protects against sepsis (By similarity).
Synonyms: DJ-1; DJ1; GATD2; HEL-S-67p
Tractability: Small molecule: a structure with a bound ligand is known; a high-quality ligand is known; it has a binding pocket of medium quality. Antibody: UniProt places it where antibodies can reach, with medium confidence; its Gene Ontology location is reachable by antibodies, with medium confidence. PROTAC: UniProt records ubiquitination sites on it; ubiquitination databases record sites on it; its protein half-life has been measured; a small molecule that binds it is known.
Target class: Enzyme; Hydrolase
Chemical probes: JYQ-173 (high quality)
Gene: Protein-coding gene on chromosome 1 (7,954,264 to 7,985,505, forward strand). Ensembl gene ENSG00000116288.
Subcellular location: Cell membrane; Cytoplasm; Nucleus; Membrane raft; Mitochondrion; Endoplasmic reticulum
Subcellular location (Human Protein Atlas): Cytosol; Nucleoplasm; Flagellar centriole; Mid piece
Pathways (Reactome):
Autophagy: Aggrephagy; Chaperone Mediated Autophagy; Late endosomal microautophagy
Metabolism of proteins: SUMOylation of transcription cofactors
Gene Ontology:
Molecular function: cadherin binding; copper ion binding; cupric ion binding; cuprous ion binding; cytokine binding; DNA-binding transcription factor binding; double-stranded DNA binding; enzyme activator activity; enzyme binding; glyoxalase (glycolic acid-forming) activity; identical protein binding; kinase binding; L-dopa decarboxylase activator activity; mercury ion binding; mRNA binding; nuclear androgen receptor binding; oxidoreductase activity, acting on peroxide as acceptor; peptidase activity; peptidase inhibitor activity; protein binding; protein deglycase activity; protein homodimerization activity; scaffold protein binding; signaling receptor activator activity; signaling receptor binding; and 11 more
Biological process: androgen receptor signaling pathway; cellular detoxification of aldehyde; cellular detoxification of methylglyoxal; cellular response to glyoxal; cellular response to hydrogen peroxide; cellular response to oxidative stress; detoxification of copper ion; detoxification of hydrogen peroxide; DNA repair; glycolate biosynthetic process; glyoxal metabolic process; hydrogen peroxide metabolic process; lactate biosynthetic process; methylglyoxal metabolic process; negative regulation of death-inducing signaling complex assembly; negative regulation of endoplasmic reticulum stress-induced intrinsic apoptotic signaling pathway; negative regulation of extrinsic apoptotic signaling pathway; negative regulation of gene expression; negative regulation of hydrogen peroxide-induced neuron intrinsic apoptotic signaling pathway; negative regulation of intrinsic apoptotic signaling pathway in response to hydrogen peroxide; negative regulation of neuron apoptotic process; negative regulation of nitrosative stress-induced intrinsic apoptotic signaling pathway; negative regulation of oxidative stress-induced intrinsic apoptotic signaling pathway; negative regulation of oxidative stress-induced neuron intrinsic apoptotic signaling pathway; negative regulation of proteasomal ubiquitin-dependent protein catabolic process; and 38 more
Cellular component: adherens junction; chromatin; cytoplasm; cytosol; endoplasmic reticulum; extracellular exosome; mitochondrion; nucleoplasm; nucleus; perinuclear region of cytoplasm; PML body; axon; membrane raft; plasma membrane; cell body; mitochondrial intermembrane space; mitochondrial matrix; neuron projection; synaptic vesicle
Genetic constraint (gnomAD): Loss-of-function variants: 13 observed, 20.16 expected, observed/expected ratio (o/e) 0.64, 90% interval 0.42 to 1.02. The upper end of that interval is the gene's LOEUF score, 1.02, which puts it in group 4 of 6, group 1 being the genes least tolerant of losing a copy. Missense variants: 234 observed, 249.77 expected, observed/expected ratio (o/e) 0.94, 90% interval 0.84 to 1.04. Synonymous variants: 98 observed, 89.1 expected, observed/expected ratio (o/e) 1.1, 90% interval 0.93 to 1.3.
Gene-disease validity (ClinGen):
ClinGen rates the evidence that PARK7 causes each of these diseases.
Parkinson disease (autosomal recessive): Definitive. A progressive degenerative disorder of the central nervous system characterized by loss of dopamine producing neurons in the substantia nigra and the presence of Lewy bodies in the substantia nigra and locus coeruleus.
Homologues: Orthologues: macaque PARK7 (100% identical), chimpanzee PARK7 (99% identical), pig PARK7 (96% identical), guinea pig PARK7 (93% identical), mouse Park7 (92% identical), dog PARK7 (86% identical), zebrafish park7 (83% identical), rabbit PARK7 (81% identical), tropical clawed frog park7 (77% identical), Drosophila melanogaster DJ-1alpha (54% identical), Caenorhabditis elegans djr-1.1 (52% identical), Drosophila melanogaster dj-1beta (52% identical), and 1 more.
Diseases named in the same sentence as PARK7 in open-access papers:
PARK7 is named in the same sentence as 294 diseases in open-access papers, as found by Europe PMC text mining. Sharing a sentence is not in itself a finding about the gene and the disease. The quoted sentences say what the papers report.
Parkinson disease (506 papers, 2004 to 2026). "Under oxidative stress conditions, VDAC’s interaction with the IP3R-Grp75 complex is further stabilized by the Parkinsonism-associated deglycase DJ-1 (also known as PARK7), which supports mitochondrial quality control processes such as mitophagy." (PMID 41415310, 2025). "Mutations in PARK7, encoding for DJ-1, lead to an imbalance in mitochondrial dynamics and culminate in the progression of neurodegenerative disorders such as Parkinson’s disease (PD)." (PMID 40608842, 2025). "DJ-1 is the product of a novel oncogene initially identified in Parkinson’s disease and is associated with autosomal-recessive hereditary Parkinson’s disease, also known as Park7 or DJ-1." (PMID 40565068, 2025). "Astrocytes are known to be become reactive in Parkinson’s disease that includes neuroinflammation, and several genes implicated in Parkinson’s are expressed in both astrocytes and neurons (e.g., PARK7, SNCA, PLA2G6, ATP13A2, LRRK2, PINK1, and PARK2)." (PMID 40972575, 2025). "The Parkinsonism-associated deglycase (DJ-1) protein protects neurons against oxidative stress-induced damage in Parkinson’s disease." (PMID 40722958, 2025). "The hub genes connecting these processes included parkinsonism‐associated deglycase (Park7), peroxiredoxin 6 (Prdx6), Jun proto‐oncogene (Jun), and calreticulin." (PMID 41164797, 2025). "To further evaluate model performance and biological relevance in specific diseases, we analyzed Parkinson’s disease-associated PARK7/DJ-1 (UniProt: Q99497), whose loss-of-function mutations cause early-onset autosomal recessive Parkinson’s." (PMID 41016015, 2025). "DJ-1, which is encoded by the PARK7 gene, was first discovered in individuals with Parkinson's disease, where it is associated with worsening oxidative stress and contributing to the degeneration of dopaminergic neurons." (PMID 40626806, 2025). "Mutations in human DJ-1 (PARK7) have been implicated in the deregulation of mitochondrial homeostasis, a critical cellular etiology observed in Parkinson’s disease progression." (PMID 40608842, 2025). "In 2001, deglycase DJ-1 (PARK7) mutation was mapped in a family with multiple consanguinity from Netherlands with early-onset parkinsonism; since then, at least 27 variants of DJ-1 have been registered." (PMID 40362688, 2025). "PARK7 encodes DJ-1, a mutation of which is a rare reason of early-onset recessive Parkinson’s disease." (PMID 38585359, 2024). "For example, one of the top implicated genes, PARK7, is a deglycase studied in the context of Parkinson’s disease, but has recently been shown to modulate regulatory T cell function." (PMID 39302339, 2024). "PARK7/DJ-1, implicated in Parkinson’s disease and solid organ malignancies, presented with a good accuracy in identifying PC when compared to CA 19-9 (AUC 0.6647)." (PMID 39767746, 2024). "Another protein associated with PD is parkinsonism-associated deglycase 7 (PARK7, also formerly known as DJ-1), which has been shown to increase its activity through persulfidation." (PMID 39728543, 2024). "DJ-1 (encoded by PARK7) was first identified as a protein associated with Parkinson's disease, but it has since been demonstrated to serve as a key cytoprotective factor in a variety of cellular contexts." (PMID 39742003, 2024). "Here, we report thedevelopment of such a chemical toolbox for the human Parkinson diseaseprotein 7 (PARK7/DJ-1) implicated in Parkinson’s disease andcancers." (PMID 38713163, 2024). "Parkinson disease (autosomal recessive, early onset) 7, also known as PARK7 or DJ-1, was initially identified in association with a form of Parkinson’s disease." (PMID 39519712, 2024). "Another example indicating mitochondrial driven parkinsonism, are mutations in the gene coding for DJ1 (PARK7)." (PMID 37951933, 2023). "PARK7 or DJ-1 was initially implicated in Parkinson disease but has been used as a biomarker for other neurodegenerative disorders." (PMID 36721240, 2023).
Parkinson disease (continued). "Loss-of-function mutations in PARK7 are associated with early-onset, recessive forms of Parkinson’s disease." (PMID 37190500, 2023). "A mutation in the gene expressing PARK7 is also associated with an autosomal recessive form of early-onset Parkinson’s disease." (PMID 37511304, 2023). "DJ-1, also known as Parkinson’s disease protein 7 (PARK7), is a multifunctional protein associated with Parkinson’s disease, cancer, oxidative stress response, and mitophagy." (PMID 37508510, 2023). "Pathological variants of PARK7 (DJ-1) have been reported in individuals with early onset Parkinson disease." (PMID 36721240, 2023). "6-OHDA was found to induce secretion of PARK7/DJ-1 which is a Parkinson disease- and cancer-associated protein that functions as a multifunctional protein involved in gene transcription regulation and anti-oxidative defense." (PMID 35512017, 2022). "The present study will offer an in-depth analysis of mutations on the structure of PARK7 and their possible implication in Parkinson’s disease." (PMID 35207708, 2022). "Among the top predictions in zebrafish are genes associated with human diseases including Parkinson’s disease (PARK7), cancer (APC, a known tumor suppresion gene) and kidney failure (PKD2)." (PMID 36158574, 2022). "PARK7 loses its functionality when it becomes mutated, and it is related to mitochondria dysfunction, resulting in the early onset of Parkinson’s disease." (PMID 35207708, 2022). "The detailed understanding of PARK7 mutations will help make therapeutic strategies for associated diseases, including Parkinson’s disease." (PMID 35207708, 2022). "Biallelic variants in DJ-1 (oncogene Dj1, MIM*602533) cause a rare Parkinsonism (PARK7, MIM#606324), the third most common AR PD after the PRKN- and PINK1-related forms, accounting for the 0.4 and 1% of EOPD cases, respectively." (PMID 34630269, 2021). "Parkinsonism associated deglycase (more commonly known as DJ-1 or PARK7) gene expression was only significantly increased in TBI/DM group suggesting small synergistic effect." (PMID 34013450, 2021). "DJ-1 was originally identified as an oncogene product while mutations of the gene encoding DJ-1/PARK7 were later associated with a recessive form of Parkinson’s disease." (PMID 34206441, 2021). "DJ-1 [also known as Parkinson’s disease (autosomal recessive, early onset) 7 (PARK7)] was originally found to be linked to an early-onset autosomal recessive form of Parkinson’s disease." (PMID 33996908, 2021). "Autosomal recessive mutations in PARK7 encoding DJ-1 are linked to a rare, familial type of early-onset Parkinsonism." (PMID 34657636, 2021). "This analysis revealed that the genes implicated in Parkinson’s disease (Atp5a1, Ndufa7, Ndufb2, Ndufs8, Park7, Cox7a2, Cox7c, Cox6b1, Cycs, Uchl1) were upregulated in thia-exposed mice (p-value = 4.2E-3)." (PMID 34295895, 2021). "PARK7 is shown to be one of the genes, the mutation of which leads to a familial form of Parkinson’s disease with autosomal recessive inheritance." (PMID 33429934, 2021). "Recent studies indicate that LAMP2A stability is controlled by the presence of DJ-1/PARK7 (Parkinsonism-associated deglycase), since DJ-1 deficiency is associated with a higher degradation rate of LAMP2A in Parkinson disease (PD)." (PMID 31623164, 2019). "It was originally identified as an oncogene, and its mutations cause a familial type of Parkinson’s disease-PARK7." (PMID 31114478, 2019). "PARK7 /DJ-1 gene mutations are linked to autosomal recessive and early-onset clinical manifestations of Parkinson's disease." (PMID 30048497, 2018). "Mutations in PARK7, which encodes the protein deglycase DJ-1, cause early-onset recessive Parkinsonism." (PMID 29599708, 2018). "Human DJ-1 (also known as PARK7) is a highly conserved, yet enigmatic protein mutated in some familial forms of Parkinson’s disease." (PMID 28246362, 2017).